CCDC197 (coiled-coil domain containing 197)
Synonyms: C14orf48; LINC00521; c14_5713
Tractability: No criterion of Open Targets' tractability assessment is met for any kind of drug.
Gene: Protein-coding gene on chromosome 14 (93,987,225 to 94,008,863, forward strand). Ensembl gene ENSG00000175699.
Gene Ontology:
Molecular function: protein binding
Homologues: Orthologues: chimpanzee CCDC197 (97% identical), pig CCDC197 (64% identical), macaque CCDC197 (62% identical), dog CCDC197 (61% identical).
Diseases named in the same sentence as CCDC197 in open-access papers:
CCDC197 is named in the same sentence as 1 disease in open-access papers, as found by Europe PMC text mining. Sharing a sentence is not in itself a finding about the gene and the disease.
CCDC197 shares sentences with these, for which no sentence is quoted: lung disease (1 paper).